FMR1 (fragile X messenger ribonucleoprotein 1)
Diseases named in the same sentence as FMR1 in open-access papers (continued):
Sharing a sentence is not in itself a finding about the gene and the disease.
premature ovarian failure (32 papers, 2007 to 2025). "They found no negative effect on response to ovarian stimulation for normal and intermediate length alleles, while others reported an association between premature ovarian failure and increased occurrence of gray zone FMR1 alleles." (PMID 40244008, 2025). "Mutations in the FMR1 gene, located onthe X chromosome, cause various diseases, including premature ovarian failure." (PMID 39835794, 2025). "Since the primary reproductive defect in females with FMR1 mutation is premature ovarian failure, gonadal origin was proposed." (PMID 36909303, 2023). "Specifically, one female PD patient with GZ allele of FMR1 CGG repeat expansions manifested with premature ovarian failure." (PMID 37583466, 2023). "Women with FMR1 mutations comprise the majority of known genetic causes of premature ovarian failure." (PMID 36909303, 2023). "Premutation range CGGn repeats of the FMR1 gene denote risk toward primary ovarian insufficiency (POI), also called premature ovarian failure (POF)." (PMID 28454580, 2017). "Later, FMR1 premutations were unexpectedly found associated with two other distinct phenotypes: primary ovarian insufficiency and tremor-ataxia syndrome." (PMID 27916885, 2016). "Primary ovarian failure (POF) has been associated with deletions of the FMR1 gene (POF1) at Xq26–q28 and the DIAPH2 gene (POF2A) at Xq21.33." (PMID 24778889, 2014). "A so-called premutation-range genotype (CGGn=55–200) of the FMR1 gene has for decades been associated with highly increased risk towards primary ovarian insufficiency (POI), also called premature ovarian failure (POF)." (PMID 23948096, 2013). "In women, the premutation range genotype of FMR1 has for decades been known associated with greatly increased risk towards premature ovarian failure (POF), often also called primary ovarian insufficiency (POI)." (PMID 22984553, 2012). "As the only not neuro-psychiatric complication of the classical premutation genotype, the FMR1 gene has for decades also been known associated with increased risk for premature ovarian failure (POF), now also frequently called primary ovarian insufficiency (POI)." (PMID 22438971, 2012). "Some studies suggest thatchanges in FMR1 transcript levels in premutation carriers in women contribute to thedevelopment of premature ovarian failure." (PMID 39835794, 2025). "After creating a premature ovarian failure model using cyclophosphamide, weinvestigated the expression level of the FMR1 gene in all groups." (PMID 39835794, 2025). "The female patient in Case 2 was diagnosed with premature ovarian failure due to the FMR1 premutation and underwent two cycles, resulting in the retrieval of three oocytes and the preservation of two unaffected embryos." (PMID 40170048, 2025). "In brief, our results and previous studies showed that theexpression level of FMR1 gene was investigated in premature ovarian failure diseaseand the results showed increased expression of FMR1 gene mRNA in ovaries." (PMID 39835794, 2025). "The association between the FMR1 premutation (50-200CGG repeats) and the premature ovarian failure (POF) suggests that epigenetic disorders of FMR1 can act as a riskfactor for the DOR as well." (PMID 29308622, 2018). "FMR1 gene is associated principally with three pathologies: FXS, tremor ataxia syndrome (FXTAS) and primary ovarian insufficiency (FXPOI)." (PMID 27983607, 2016). "The association between premature ovarian failure (POF) and the FMR1 repeat number (41> CGGn< 200) has been widely investigated." (PMID 17428316, 2007). "Contrary to men, premature ovarian failure in women with FMR1 mutations is not a developmental disorder." (PMID 36909303, 2023). "Among women with FMR1 premutation range CGGn, alterations in mRNA production have been suggested as a possible cause of premature ovarian failure, while no such abnormalities of mRNA production have been described for women with what is widely considered the common (i.e., normal) range of CGGn<55." (PMID 28454580, 2017).
premature ovarian failure (continued). "Phenotypic expression of aberrant triple CGG amplification of the FMR1 gene includes abnormal increases in FSH levels, premature menopause, and premature ovarian failure." (PMID 38877588, 2024). "FMR1 premutations have been found in up to 10% of cases of primary ovarian insufficiency (POI; also known as premature ovarian failure (POF) or secondary amenorrhoea, and defined as menopause before age 40)." (PMID 27916885, 2016). "Notably, FMR1, DIAPH2, POD1B, and BMP15 were previously designated as premature ovarian failure (POF) loci, namely, POF1, POF2A, POF2B, and POF4, respectively." (PMID 37033245, 2023). "Carriers of the female FMR1 premutation (when the number of CGG repeats falls between 55 and 200) or FMR2 microdeletion show menstrual dysfunction, diminished ovarian reserve, and premature ovarian failure." (PMID 31412890, 2019). "In the absence of a family history of ID, premature ovarian failure or Parkinsonism, the search for FMR1 abnormalities is usually not recommended in patients with high-functioning ASD (American Academy of Pediatrics,)." (PMID 22738402, 2012).
ovarian insufficiency (30 papers, 2007 to 2025). "One of the most prominent regulators of folliculogenesis and a common genetic cause of ovarian insufficiency is FMR1." (PMID 40244008, 2025). "The first is to determine the probable cause of ovarian insufficiency and identify carriers of mutations in the FMR1 gene." (PMID 34542254, 2022). "FMR1 testing has a dual role in patients with ovarian insufficiency: determining the probable cause of ovarian failure and identifying women at risk of transmitting mutations to their offspring." (PMID 32787884, 2020). "FMR1, located on the distal part of the long arm of the X chromosome, together with the FMRP protein, expressed mainly in neural and germ cells, is a primary regulator of folliculogenesis and one of the most common genetic causes underlying ovarian insufficiency." (PMID 40244008, 2025). "For this reason, the analysis of FMR1 CGG expansions in women with signs of ovarian dysfunction of unknown cause may prove to be a decisive and appropriate diagnostic approach." (PMID 38275588, 2023). "For this reason, it is important to analyze FMR1 gene among women presenting signs of ovarian dysfunction of unknown cause." (PMID 27983607, 2016). "However a young woman, who presented a severe ovarian failure with early onset, carried normal FMR1 alleles (<40)." (PMID 17428316, 2007). "Recommendations from various medical organizations advocate for FMR1 testing for all women exhibiting unexplained ovarian insufficiency or elevated follicle-stimulating hormone (FSH) levels before the age of 40, irrespective of family history." (PMID 39320553, 2024). "Several exceptions are worth noting: Family F8629 presented with primary amenorrhea and infertility and was found to have severe ovarian insufficiency with normal karyotype and FMR1 repeat number." (PMID 37644014, 2023). "We evaluated changes in the expression of AKT/mTOR signaling pathway genes by real time PCR in the peripheral blood of 74 patients with Premature Ovarian Insufficiency and 56 fertile controls and correlated their expression with FMR1 expression." (PMID 35248053, 2022). "Second, the age differences between groups and the fact that FMR1 premutation women with FXPOI had already developed ovarian dysfunction." (PMID 35456280, 2022). "Mitochondrial dysfunction in FMR1-dependent ovarian insufficiency has been addressed by using female mice of the 130R strain bearing an insertion of expanded CGG repeats in the Fmr1 gene." (PMID 34445074, 2021). "Although FMR1 testing has been recommended in the evaluation of the etiology of ovarian insufficiency in western countries, screening for the same among Chinese women is not warranted as the low frequency of occurrence." (PMID 32787884, 2020). "Previous studies have shown that there is an association between FMR1 CGG repeats and ovarian dysfunction." (PMID 32787884, 2020). "Further investigations with larger sample sizes is necessary to study the incidence of FMR1 expansions in all forms of ovarian insufficiency to confirm the results of this pilot study." (PMID 32787884, 2020). "For example, fragile X mental retardation-1 (FMR-1) alleles with the (CGG)n repeats were associated with neurodegeneration and ovarian insufficiency." (PMID 26196922, 2015). "This publication reviews the literature on the FMR1 gene and selected phenotypes involving ovarian dysfunction." (PMID 25071825, 2014). "Carriers of FMR1 premutation or BRCA1 mutation are at high risk of developing ovarian failure regardless of chemotherapy." (PMID 34193292, 2021). "Numerous studies have examined the association between FMR1 CGG repeats and ovarian dysfunction." (PMID 32787884, 2020). "PM, in addition, to a reduction in FMRP have an increase in FMR1 mRNA, which could aggravate the ovarian dysfunction even further." (PMID 28955201, 2017). "However, how this relates to the observation that Fmr1 KO mice also show ovarian dysfunction is unclear." (PMID 25147583, 2014).
ovarian insufficiency (continued). "Confirmation of the importance of RAN translation by-products to FXPOI will significantly increase our understanding of the disorder and could provide an avenue to understanding ovarian dysfunction in FMR1 premutation carriers." (PMID 25134882, 2014). "Additionally, of note, the number of trinucleotide repeats in the FMR1 gene was not analyzed and the patient was reluctant to undergo relevant examinations, we thus cannot rule out Fragile X-associated primary ovarian insufficiency." (PMID 40687627, 2025). "In addition, triplet repeat expansion in FMR1 is known to cause POI, although the association between FMR1 haploinsufficiency and ovarian dysfunction remains unknown." (PMID 37033245, 2023). "In summary, FMR1 premutations may not be as common a cause of ovarian failure as previous estimates suggest, but they still represent an important cause of ovarian failure and therefore give a reason to test women with POI and EM for the mutation." (PMID 23703681, 2014). "FMR1 premutations are not as prevalent in women with ovarian insufficiency as previous estimates have suggested, but they still represent a substantial cause of primary ovarian insufficiency and early menopause." (PMID 23703681, 2014). "Similar to FXTAS, oocytes in FMR1 premutation ovarian insufficiency mouse models display aberrant accumulation of protein, elevated levels of ubiquitination which reports suggest are consistent with evidence of the FMR1 gain-of-function mechanism hypothesized in FXTAS." (PMID 25134882, 2014). "Elucidating the pathophysiology of FXPOI may help in early detection of ovarian dysfunction and tailoring IVF treatments to FMR1 premutation carriers." (PMID 34238973, 2021). "It is well established that full mutation carriers, or those with an allele of >200 methylated repeats that leads to silencing of FMR1, do not suffer from ovarian dysfunction." (PMID 25147583, 2014).
Infertility (29 papers, 2010 to 2025). "Results of GLM models for the association of CGG repeats at FMR1 alleles with primary Infertility and secondary Infertility." (PMID 40600017, 2025). "In order to investigate the association of the repeats on FMR1 gene and infertility, linear regression analysis with GLM model for the CGG repeats on both alleles were performed." (PMID 40600017, 2025). "Subsequently, we investigated the relationship between FMR1 alleles and reproductive hormone levels in patients with infertility." (PMID 40600017, 2025). "This also fully illustrates that FMR1 gene mutation accounts for a relatively high proportion in the infertility population." (PMID 38562051, 2024). "Previous studies have demonstrated that the prevalence of FMR1 premutation is increased in women with DOR compared with women with other causes of infertility and oocyte donors." (PMID 39202368, 2024). "But the literature is inconsistent on the association between the FMR1 trinucleotide repeat length and infertility." (PMID 39202368, 2024). "X fragile premutation (FMR1) consists in the expansion of CGG repeat to 55 to 199 copies in untranslated FMR1 genes and is associated with a high risk of infertility and POI." (PMID 39030346, 2024). "Given that FMR1 gene mutations are also associated with reproductive disorders, combined with increasing infertility rates, it is critical to examine FMR1 role in the reproductive axis." (PMID 36909303, 2023). "FMR1 sub-genotypes distribution revealed that 32% of the infertile females had an allele with CGG > 34 and 36% had CGG < 26, as opposed to 16% and 44%, respectively, in the oocyte donor cohort." (PMID 33530161, 2021). "Female genetic diagnostics for infertility comprise karyotyping, analysis of the FMR1 premutation and a gene panel including genes associated with congenital hypogonadotropic hypogonadism (CHH) or congenital adrenal hyperplasia." (PMID 38836211, 2021). "Millions of people globally are at high risk for neurodegenerative disorders, infertility or having children with a disability as a result of the Fragile X (FX) premutation, a genetic abnormality in FMR1 that is underdiagnosed." (PMID 28572606, 2017). "The distribution pattern seen in oocyte donors, therefore, likely is typical for young normal female populations, suggesting in young women an approximately 22% prevalence of low FMR1 alleles but a much higher prevalence in older infertile women." (PMID 25019151, 2014). "In infertile women FMR1 mutations (genotypes/sub-genotypes) have previously been demonstrated predictive of IVF pregnancy chances." (PMID 25019151, 2014). "Assessing young oocyte donors and infertile women at different ages, using these newly defined FMR1 alleles, ovarian functions of the gene came into clearer view: different FMR1 alleles were found associated with fairly typical ovarian aging patterns." (PMID 25221568, 2014). "The literature is inconsistent on the association between the FMR1 repeat length and infertility due to low ovarian reserve." (PMID 25071825, 2014). "IVF outcomes were investigated in a private infertility center in reference to patients' FMR1 mutations based on a normal range of CGGn = 26–34 and sub-genotypes high (CGGn>34) and low (CGG<26)." (PMID 25019151, 2014). "Once again, the increasing prevalence of low alleles, comparing young donors and older infertile women points towards a potential association of low FMR1 alleles with infertility at advanced ages." (PMID 25019151, 2014). "The literature is inconsistent on the association between the FMR1 trinucleotide repeat length and infertility." (PMID 25071825, 2014). "Low FMR1 alleles in infertile women have also been associated with abnormal immune laboratory findings in infertile women, suggestive of immune system activation." (PMID 25019151, 2014).
Infertility (continued). "Here presented data, therefore, are in agreement with previously published FMR1 data in older infertile patients, which suggest that a low allele is prognostically predictive of PRFOR and poorer pregnancy chances." (PMID 23948096, 2013). "These associations also translate into clinical significance for infertile women since the FMR1 genotype appears predictive of pregnancy chances with IVF." (PMID 21179569, 2010). "The mutation of the FMR1 gene may drive premature depletion of follicles, thereby shortening the reproductive lifespan, ultimately leading to secondary infertility." (PMID 40600017, 2025). "Overall, the high normal sized (35–44 CGG) repeat length at both FMR1 alleles may serve a promoting role in the development of secondary infertility in Asian women." (PMID 40600017, 2025). "A high number of FMR1 mutations has been associated with infertility and may thus contribute to these findings in Asian women." (PMID 35937455, 2022). "Using a logistic regression model, in young infertility patients under age 38 years, odds of clinical pregnancy, however did differ significantly between patients with single low FMR1 alleles and those with only norm and/or high alleles (OR 2.244; 95%CI 1.168, 4.312; P = 0.015)." (PMID 25019151, 2014). "In a study of 339 infertility patients we previously demonstrated that different races were associated with different distributions of FMR1 genotypes and sub-genotypes, and that genotypes and sub-genotypes in different races were associated with varying IVF pregnancy chances." (PMID 22963248, 2012). "This study confirms close associations between FMR1 genotypes and ovarian function but for the first time also associates FMR1 genotypes in infertile women with risk towards autoimmunity and with pregnancy chances in association with in vitro fertilization (IVF)." (PMID 21179569, 2010). "Results of multivariate logistic regression models with categories of FMR1 CGG repeat numbers for infertile patients." (PMID 40600017, 2025). "As a consequence, research on the FMR1 gene has extended to other endpoints of reproductive health, including infertility and ovarian reserve." (PMID 40600017, 2025). "Typically, most women have 5–44 CGG repeats in their FMR1 genes; however, studies have shown that infertile women with a diminished ovarian reserve are more likely to have ≥35 FMR1 CGG repeats." (PMID 35937455, 2022). "To complement the infertility genetic panel with FMR1 study, we used an already available protocol based on PCR amplification and capillary electrophoresis." (PMID 32155011, 2020). "The aim of this study was to analyze the mRNA expression and epigenetic alteration (histoneacetylation/methylation) of the FMR1 gene in blood and granulosa cells of 20 infertile women." (PMID 29308622, 2018). "Following the confirmation of the association between the FMR1 premutation and POF, publications appeared on the relationship between ovarian hormones, infertility and this gene." (PMID 25071825, 2014). "They, however, suggest an increasingly important impact of the FMR1 gene on ovarian aging and female fertility and infertility." (PMID 25019151, 2014). "Until such data become available, it appears prudent to consider the FMR1 genotype of infertility patients." (PMID 21526209, 2011). "Since ovarian reserve at all ages greatly affects treatment success of infertile patients, FMR1 genotypes should, therefore, demonstrate significant impact on treatment outcomes." (PMID 21526209, 2011). "This study shows that the prevalence of premutation of the FMR1 gene in women younger than 35 years of age with infertility and low ovarian reserve markers according to POSEIDON criteria was higher ((7.69%) than in the controls (oocyte donors; 1.32%, p = 0.012))." (PMID 39202368, 2024). "Specifically, we tested the hypothesis that FMR1 premutation study should be determined in infertile young patients with DOR in order to give them adequate genetic counselling." (PMID 39202368, 2024).